TIMP1 (TIMP metallopeptidase inhibitor 1)
Diseases named in the same sentence as TIMP1 in open-access papers (continued):
Sharing a sentence is not in itself a finding about the gene and the disease.
tumor (continued). "Since neutrophils do not produce TIMP-1 or gelatinase A, in contrast with monocytes and tumor cells, they are known to be a main source of MMP-9 for biochemical and biological studies." (PMID 35273488, 2022). "To assess gene expression profiles associated with mitochondrial function in NSCLC and characterize the relationship between TIMP-1 and altered mitochondrial function, we compared NSCLC patient-derived tumor tissue and adjacent normal tissue targeting mitochondrial-related genes." (PMID 36230997, 2022). "With respect to its MMP-dependent functions, TIMP-1 can play a negative role in tumour cell adhesion and inhibit the degradation of ECM and basement membranes facilitated by MMPs." (PMID 33628641, 2021). "Positive and/or negative effects of adiponectin, IL-6, IL-8, MCP-1 and TIMP-1 on carcinogenesis, tumor development and metastasis, as well as on the efficacy of the treatment are described." (PMID 34572929, 2021). "Overexpression of TIMP-1, TIMP-2, and TIMP-3 reduces tumor growth." (PMID 35201460, 2021). "TIMP1 inhibits the protein hydrolytic activity of MMP and plays a role in the balance of matrix remodeling during extracellular matrix degradation, which has an important role in tumor invasion and metastasis." (PMID 35141140, 2021). "Interestingly, both Mon_1 and Mon_3 also expressed the matrix metalloproteinase inhibitor TIMP1 and CXCL5 (the ligand for CXCR2) that promote recruitment of suppressive granulocytes and enhance tumor growth in mice." (PMID 34921160, 2021). "They found that elevated systemic levels of TIMP-1 created a pre-metastatic environment in the liver that diverted tumor cells to this organ but not others." (PMID 35097136, 2021). "Based on our results, we can suggest greater utility of serum TIMP-1 compared with MMP-9, MMP-2, and TIMP-2 in the diagnosis of CRC, particularly in the assessment of the tumor stage, survival of cancer patients, resectability of the tumor, and in the differentiation between CA and CRC." (PMID 34071492, 2021). "An immunohistochemical study of MMP-7, -14 and TIMP-1 was performed on sporadic CRC (n = 86), IBD-associated CRC (n = 23) and colorectal mucosa of non-tumor samples from IBD patients without (n = 47) and with (n = 23) associated CRC." (PMID 33946534, 2021). "The authors suggest that the oncogenic effect of MMP-9 in this type of tumor is not due to its elevated expression but to decreased inhibition by TIMP-1, whose expression is significantly reduced." (PMID 35097136, 2021). "Cannabinoids also curtail tumor invasion and metastasis by inhibiting the secretion of matrix metalloproteinase (MMP)-2 and MMP-9, while increasing the tissue inhibitors of MMP-1 (TIMP-1)." (PMID 33066359, 2020). "Expression of matrix metalloproteases 2, 9 and 14 (MMP-2, MMP-9, MMP-14), tissue inhibitors of metalloprotease 1 and 2 (TIMP-1, TIMP-2) and vascular endothelial growth factor A (VEGF-A) is involved in tumor invasion and metastasis via extracellular matrix degradation and angiogenesis." (PMID 32669083, 2020). "Instead Timp1, the inhibitor of the matrix metalloproteinase 2 MMP2, was downregulated in U87AKDAPLNKO GBMs compared to the wildtype situation, and MMP2 itself, a proteinase degrading the extracellular matrix to support tumor cell invasion, was upregulated." (PMID 32545380, 2020). "Apart from confirming targets, such as ERBB2 and S100A11, which are exclusively upregulated in the tumour epithelial cells, qPCR data confirmed that stromal targets such as SPARC, TIMP1, IGFBP7, COL1A1 were upregulated specifically in stromal components and not in epithelial components." (PMID 31959771, 2020).
tumor (continued). "Once the dynamic balance between TIMP1 and MMP9 is broken, it may promote tumor invasion and metastasis." (PMID 33144895, 2020). "Furthermore, consistent with the in vitro data, we confirmed that phosphorylation of p38MAPK was suppressed by α-H treatment in tumor tissues and reported the downregulation of MMP-9 and a significant increase in TIMP-1 expression." (PMID 31551765, 2019). "TIMP1 mRNA is nearly absent in platelets from healthy humans, but is increased in platelets from tumor patients." (PMID 31639773, 2019). "The significant expression of TIMP-1 and CINC-1 cytokines in co-culture media of K562 cell and BMSCs suggests that these cytokines could be involved in the inhibition of the tumor cell proliferation via BAX and caspase-3 cascade." (PMID 31009502, 2019). "A significant increase in the odds ratio for survival occurred in the case of increased expression of MMP-9 investigated in the tumor and MMP-2 and TIMP-1 in the stroma; however, the chance of the patient’s survival increased most clearly in relation to TIMP-1P [OR=1.724]." (PMID 31223594, 2019). "On the contrary, the expression of TIMP-1 in EOC tumor biopsies was reported to be not predictive of OS in EOC patients." (PMID 31861382, 2019). "MMP-2 and TIMP-1 were mostly expressed in the proximity of blood vessels and inflammatory cells in tumour-invaded areas, but was not seen in tumour-free areas." (PMID 29623449, 2018). "TIMP-1 is increasingly recognized as a molecule with a variety of pro-tumorigenic functions, e.g. TIMP-1 can bind to the tetraspanin CD63 and promote liver metastases via both, host-mediated mechanisms as well as direct effects on tumor cell aggressiveness." (PMID 29394913, 2018). "In specific, TIMP1 signaling via CD63 leads to activation of hepatic stellate cells, which create a pre-metastatic niche in the liver allowing efficient metastasis to this organ, and also induces a tumor-promoting stress response in tumor cells." (PMID 29394913, 2018). "It was demonstrated that MMPs are particularly important for the processes of tumor invasion and progression, and elevated preoperative serum MMP2, MMP9, and TIMP1 concentrations constitute a strong prognostic factor of poor prognosis among patients with colon cancer." (PMID 29304854, 2018). "The aim of this study was to prospectively validate a gene expression panel (composed of GAPDH, VIL1, CLU, TIMP1, TLN1, LOXL3 and ZEB2) for detecting circulating tumor cells (CTCs) as prognostic and predictive tool in blood samples from 94 metastatic CRC (mCRC) patients." (PMID 28608814, 2017). "Glycosylated TIMP-1, but not aglycosylated one, exerts influence of tumor formation and growth in the early phase." (PMID 28454584, 2017). "Tumor angiogenesis is stimulated by the influx of neutrophils that release highly angiogenic pro-MMP9 free of TIMP1, the natural inhibitor of MMP9, or M2 macrophages expressing high levels of pro-MMP9 and low levels of TIMP1." (PMID 28423685, 2017). "In summary, these results indicate that MMP-2 and TIMP-1 possibly aided by c-MET may promote tumor progression by enhancing angiogenesis and tumor invasion." (PMID 28234925, 2017). "In addition, Timp1 and AKT act synergistically to confer anoikis resistance in advanced tumor stages." (PMID 28430130, 2017). "Overall our observations demonstrate increased expression of host- and tumor-derived TIMP-1 in our prometastatic model, suggesting that TIMP-1 may play an important role in mediating the aggressive behavior seen in the subclone." (PMID 29137288, 2017). "The 4C11+ cell line is extremely aggressive and, after 12 days, we noted tumor growth in animals inoculated with control cells, but not with Timp1 silenced cells." (PMID 28430130, 2017).
tumor (continued). "In 4T1 tumor section specimens, we found that 150 mg/kg decreased MMP-9 to 38.54% compared with 75% in the control group, increased TIMP-1 to 76.04% compared with 31.25% in the control group, and increased TIMP-2 to 66.15% compared with 33.33% in the control group, respectively." (PMID 28088791, 2017). "Similar to both MMP-2 and c-MET, TIMP-1 positive cells were present around blood vessels as well as in areas of necrosis, and similar to MMP-2, cells expressing TIMP-1 were also observed in the tumor periphery." (PMID 28234925, 2017). "When tumor cells are exposed to cetuximab, expression of TIMP-1 will be inhibited, irrespective of KRAS status." (PMID 27509063, 2016). "The multiple level of interactions that exist in EGF signaling, RAS, and cell survival, proliferation and invasion, indicated that high plasma TIMP-1 levels may interact with EGFR signaling and thereby affect the anti-tumor effects of EGFR inhibitors." (PMID 27509063, 2016). "Compared to the 10 proteins (GM-CSF, IGFBP-1, IGFBP-3, PTX-3, PDGF-AA, serpin E1, PEDF, TIMP-1, TIMP-4 and uPA) detected in the plasma of MDA-MD-231_WT tumor bearing mice, only 2 (serpin E1 and TIMP-1) were detected in the plasma of MCF-7_WT tumor bearing mice." (PMID 27995973, 2016). "The tissue inhibitor of matrix metalloproteases (TIMP)-1 (a regulator of extracellular matrix modulation with cytokine-like properties) was engineered to contain a GPI anchor and was delivered to different tumor cell lines by MP." (PMID 27542385, 2016). "The TIF secretome was, for the most part, distinctly different from the plasma secretome, although some factors such as TIMP-1, IGFBP-1, PTX3, uPA and IGFBP-3 were observed in both TIF and plasma and may provide plasma biomarkers of the tumor secretome." (PMID 27995973, 2016). "From a panel of 55, only 4 factors (serpin E1, TIMP metallopeptidase inhibitor 1 (TIMP-1), urokinase plasminogen activator (uPA), and VEGF) were detectable in TIF derived from MCF-7_WT and MCF-7_VEGF tumors and the plasma from these tumor-bearing mice." (PMID 27995973, 2016). "In addition to laminin-111, tumor cells growing alone secreted laminin-5, perlecan, MMP-7, TIMP-1 and CD44." (PMID 25885552, 2015). "When this protein was positive only 22.2% of cases had biochemical recurrence whereas tumor recurrence occurred in 56.3% when TIMP-1 was negative (p=0.048) (Table-4)." (PMID 26742965, 2015). "Due to its MMP inhibitory activity, TIMP-1 was initially thought to have major, more recent studies have demonstrated that TIMP-1 may also promote tumor growth in an MMP-independent manner by stimulating cancer cell growth and inhibiting apoptosis." (PMID 24978435, 2014). "We performed a protein array on tumor explant supernatants and found a significant decrease of monocyte chemotactic protein (1 MCP1) (CCL2), IL6, and tissue inhibitor of metalloproteinase (1 TIMP1) expression in cells expressing DNIIR." (PMID 25280532, 2014). "Also included are proteins previously implicated in tumor progression in other cancer types (e.g., CTGF, TIMP1, S100A10) and proteins that we have identified in proteomics screens of other tumor models (unpublished data)." (PMID 24618895, 2014). "TIMP-1 and TIMP-2 have the ability to inhibit tumor invasion and metastasis." (PMID 25120710, 2014). "Third, SAA may enhance tumor cell invasion and metastatic spread by becoming directly involved in enhancing the activity of matrix degrading enzymes (MMP/TIMP-1) and by increasing TNFα production in and through its association with collagen cleavage in vivo." (PMID 24447576, 2014). "Activation of TIMP-1 free gelatinase B/MMP-9 releases angiogenic factors stored within the extracellular matrix, which promote endothelial sprouting and new vessel formation, and gelatinase B/MMP-9-assisted tumour cell intravasation and dissemination." (PMID 24473089, 2014).
tumor (continued). "To test whether increased expression of TIMP-1 induces expression of the EMT markers, we analyzed the tumor sections derived from the in vivo experiments for the expression of Snail, Slug, MMP-2, and MMP-9." (PMID 24143225, 2013). "Preoperative KAP1, TIMP1 and STC2 expression levels in peripheral blood were related to cancer stage and may be markers of tumor invasion, lymph node metastasis and TNM stage." (PMID 23548070, 2013). "In most of these studies it was found that stage I, II and III CRC patients had the same degree of TIMP-1 elevation as compared to non-neoplastic individuals and thus the plasma level was not related to tumor burden." (PMID 24107468, 2013). "In that study, TIMP-1 present in tumor tissue in an unbound form appeared not to be related with a poor outcome, whereas increasing amounts of complex-bound TIMP-1 was related with a shorter recurrence-free and overall survival." (PMID 24330623, 2013). "This may have been due to the decrease in the protein expression of MMP-9, PCNA and VEGF, and the increase in the TIMP-1 protein expression induced by SN50, in combination with the cytotoxicity of SN50 towards the tumor cells." (PMID 24137341, 2013). "In addition to serving as a naturally occurring inhibitor of MMPs, TIMP-1 also displays several MMP-independent effects, including promoting tumor proliferation and angiogenesis, and inhibiting apoptosis." (PMID 24143225, 2013). "Crosslinking of collagen by LOXL2 may stimulate matrix metalloproteinases such as MMP9 and TIMP1 to implement ECM remodeling (interaction 20), thereby facilitating tumor cell migration." (PMID 22570691, 2012). "In a handful of studies investigating the suppressive effect of TIMP-1 on tumor cell proliferation and metastasis, mice have been treated with recombinant human TIMP-1 (rhTIMP-1) protein at doses of 2–50 mg/kg with no reported toxicity." (PMID 23185522, 2012). "TIMP-1 stands out as a soluble factor which does not only modulate the extracellular matrix by regulation of MMP-activity but as an inducer of HIF-1α, it also decides over cell fate by guiding tumor cells toward an invasive phenotype." (PMID 22807917, 2012). "This analysis revealed that integrin β3, PlGF, Nur77, TIMP-1, and t-PA were absent in the majority of normal healthy kidney endothelium samples, while being present in the tumor endothelium." (PMID 22235379, 2011). "We performed analyses including TIMP-1 both as a continuous log-transformed variable and as a dichotomized variable with patients divided into two groups of high and low tumor tissue TIMP-1 levels, respectively, by the median TIMP-1 concentration of the total patient group." (PMID 19744322, 2009). "Some recent studies suggest that tissue inhibitor of metalloproteinases-1 (TIMP-1) and gelatinase B (MMP-9) could be utilized as novel tumor markers in the determination of prognosis in the carcinomas of head and neck, breast, ovary, and colon." (PMID 19662197, 2007). "Plasma concentrations from patients with metastasized tumours showed statistically significant higher values for TIMP1 compared to samples from non-metastasized tumours." (PMID 16901349, 2006). "Matrix metalloproteinase-8 and TIMP-1 were also significantly increased, whereas tumour TIMP-2 levels were found not to be enhanced." (PMID 16538217, 2006). "At the same confidence interval, TIMP-1 and TIMP-3 also correlated with increasing tumour grade." (PMID 16465195, 2006). "A previous study of urinary TIMP1 concentrations showed higher concentrations in muscle invasive compared with superficial tumours, and a lower MMP1 : TIMP1 ratio was found in invasive tumours." (PMID 15083203, 2004). "In this regard, we have examined the mechanisms regulating TIMP-1 expression in human prostate lines derived from nonmalignant and malignant tumours." (PMID 12771930, 2003).
tumor (continued). "TIMP-1 availability should prevent formation of MMP-9 dimers, while we found high levels of the homodimer of MMP-9 (220 kDa) and the heterodimer of MMP-9 and NGAL (135 kDa), indicating that there is unbound MMP-9 left in tumour tissue." (PMID 12085179, 2002). "The premalignant as well as the grade I tumours were consistently negative for collagenase-1 and -3 and TIMP-1 and -3." (PMID 10360651, 1999). "MMP-9 and TIMP-1 mRNA were similarly observed in the peritumour stroma cells rather than in tumour cells themselves." (PMID 7669564, 1995). "TIMP1 emerges as the only consistently overexpressed inhibitor, while TIMP4 appears as a promising prognostic marker with unique MMP correlations that may influence tumor behaviors." (PMID 41718391, 2026). "In contrast, expressions of TIMP1 and NOX4 exhibited significant positive correlations with immune infiltration, implying that these genes could be enhancing immune cell presence in the tumor microenvironment." (PMID 40290432, 2025). "So far, our results identified glycosylation macroheterogeneity as a critical determinant of the tumor-promoting cytokine-like activity of TIMP-1 via CD63, which would be one explanation for the correlation of elevated expression of double-glycosylated TIMP-1 in PC." (PMID 40345589, 2025). "Conversely, TIMP1 histoscore in stromal cells did not significantly correlate with T cell densities in the CT, but positively correlated with T cell densities in the IM and overall tumor regions." (PMID 39789100, 2025). "Furthermore, there is emerging evidence of the co-expression of TIMP1 with both CXCL8 and c-MYC, which may influence PD-L1 expression and thus, the immune escape mechanisms of tumor cells." (PMID 40290432, 2025). "Furthermore, no prior studies have examined the relationship between tumor TIMP1 expression and circulating TIMP1 levels." (PMID 39789100, 2025). "In contrast, TIMP1 expression in tumor cells showed a negative correlation T cell densities the tumor center, supporting the hypothesis that TIMP1 in carcinoma cells may act as a pro-tumor cytokine." (PMID 39789100, 2025). "The TIMP1/CD63/β1-integrin complex activates MAPK, FAK-PI3K, or YAP/TAZ signaling, which promotes cancer cell proliferation, growth, survival, migration, and EMT, regulates differentiation and inhibits apoptosis of cancer cells, ultimately leading to tumor progression and metastasis." (PMID 38360633, 2024). "We also confirmed that 4 genes (PECAM1, TIMP1, CXCL5 and PDGFB) were correlated with the expression of the VEGF family, suggesting that these genes may work together with the VEGF family to promote tumor LYM." (PMID 38638428, 2024). "For clinical validation, no significant significance was found in TIMP1 expression in tumor samples compared to normal ones (p > 0.05), which could be due to the small size of samples." (PMID 38221932, 2024). "TIMP1 (Tissue Inhibitor of Metalloproteinases 1), which is overexpressed in OC, has been shown to affect the tumor microenvironment (TME) by altering the behavior of both tumor and endothelial cells, leading to drug resistance, particularly in advanced OC patients." (PMID 38238592, 2024). "Similarly, a lack of correlation was confirmed for the patients who had tumor cells in the surrounding lymph nodes as compared to those whose lymph nodes were free (TIMP1, p = 0.6652; MMP2, p = 0.5166; MMP9, p = 0.9766; collectively, p = 0.8416)." (PMID 37509417, 2023). "However, there is evidence that if there is excessive TIMP1 in the tissue, it may activate other MMPs, such as MMP-3, or promote tumor invasion and metastasis through other modes of action." (PMID 36158681, 2022). "Caffeic acid also increased mRNA levels of TIMP-1 and TIMP2 (tissue inhibitors of metalloproteinases 1 and 2), and decreased mRNA levels of VEGFA (vascular endothelial growth factor A), metalloproteinases MMP-2, and MMP-9, essential for aggressive tumor growth and metastases." (PMID 36614030, 2022).